LAG3 (lymphocyte activating 3)
Diseases named in the same sentence as LAG3 in open-access papers (continued):
Sharing a sentence is not in itself a finding about the gene and the disease.
tumor (continued). "The level of LAG3 expression was higher in the high-risk group compared to the low-risk group, demonstrating the potential effect of LAG3 on shaping the tumor immune microenvironment." (PMID 35300596, 2022). "High levels of LAG-3 expression have been associated with tumor progression, poor prognosis, and unfavorable clinical outcomes in various types of cancer." (PMID 36551630, 2022). "Recent studies have shown that the inhibitory function of LAG3 strongly correlates with the level of surface expression and subsequently, high LAG3, on tumor infiltrating lymphocytes, is associated with a poor prognosis." (PMID 36278613, 2022). "A recent study showed that upregulation of LAG-3 on tumor tissues was associated with a bad prognosis in CRC patients with microsatellite instability-high." (PMID 36146549, 2022). "LAG-3 overexpression in TILs and Tregs in patients’ peripheral blood is associated with T-cell depletion, as well as with tumor progression and poor clinical prognosis in many types of solid and hematological neoplasms." (PMID 36140182, 2022). "The gene expression profile data showed that LAG-3 caused T-cell exhaustion in the tumour microenvironment by cooperating with a variety of inhibitory receptors in patients with melanoma." (PMID 35494015, 2022). "Spatial analysis in bladder and gastric cancer tumor cells has demonstrated that the density and proximity of LAG-3+ were significantly greater when associated with MHC II+ vs." (PMID 34611303, 2022). "Remarkably, after narrowing the search scope to genes that were highly expressed in tumor tissues, LAG3, PDCD1, and RUFY4 were found to be associated with the high degree of immune infiltration of Tregs and TFHs." (PMID 35135552, 2022). "Similar to other UV-induced tumors, PDS are inflammatory and immunogenic tumors (with a high number of CD4+/CD8+ tumor-infiltrating lymphocytes (TILs) and checkpoint molecule expression such as PD-L1, LAG-3, TIGIT) with a very high mutational burden." (PMID 36465341, 2022). "It was observed that higher expression of LAG3 at the level of the tumor-associated lymphocyte subpopulation correlates with higher PFS as an independent predictor factor." (PMID 36013315, 2022). "In contrast, higher LAG-3 expression in the tumor has been shown to be associated with an unfavorable prognosis in oral squamous cell carcinoma, salivary gland carcinoma, pancreatic cancer and clear cell renal cell carcinoma." (PMID 36359346, 2022). "In HNSCCs, LAG-3 overexpression is associated with worse prognosis, and LAG-3 blockade retarded tumor growth in a HNSCC mouse model." (PMID 33747915, 2021). "Tumor-infiltrating T cells are also typically exposed to tumor-associated antigens and consequently express high levels of inhibitory co-receptors such as LAG-3, leading to a state of exhaustion." (PMID 34948104, 2021). "We demonstrated that LAG-3 expression on TILs was associated with a favorable DFS, especially when LAG-3 positive TILs were identified at the tumor front." (PMID 34442393, 2021). "LAG3 upregulation is strongly associated with the therapeutic effect of nivolumab in various mouse tumor models." (PMID 35111155, 2021). "Another important distinction was the tumor-associated presence (2% of CD3+ T cells) of Lag3+ Granzyme B+ cytotoxic T cells (“TcEFF_II”) within the liver but not in the lung microenvironment." (PMID 33985562, 2021). "In HNSCC, LAG3 overexpression on tumor tissue has been associated with larger tumor size, extensive lymph node involvement, and higher tumor grade." (PMID 34357118, 2021). "Taken together, our data demonstrate elevated expression levels of not only LAG3 but also of its ligands in high-risk M3 tumours." (PMID 34503258, 2021). "In DLBCL, the expression of LAG3 is the highest, and is associated with the expression of PD-L1 and tumor mutation burden, and the double block of LAG3 and TIM3 restores the function of anti-DLBCL T cells." (PMID 35111155, 2021).
tumor (continued). "LAG3-positivity was associated with an inflamed tumour micro-environment and cytotoxic T cell infiltrate." (PMID 33669038, 2021). "In particular, targeting the LAG-3 pathway has been associated with anti-tumor activity in preclinical models, providing further rationale for pharmacologic modulation of the LAG-3 axis in cancer patients." (PMID 34199722, 2021). "We confirmed that high levels of LAG3 expression in UM were positively associated with high-risk tumour parameters, such as epithelioid/mixed cell type and chromosome 3/BAP1 loss, and described an association with the presence of inflammatory cells." (PMID 34503258, 2021). "In KIRC, the expression of LAG3 mRNA and tumor-intrinsic protein are associated with methylation regulation." (PMID 35111155, 2021). "EAC patients with LoY have a poor prognosis and show correlation with the immune checkpoint protein LAG3, suggesting a direct influence of Y deficiency on the tumor immune microenvironment." (PMID 32629877, 2020). "Some works on early stage radically resected NSCLC have previously associated tumor-infiltrating lymphocytes (TILs) and immune checkpoint expression, such as programmed death ligand 1 (PD-L1) and lymphocyte activation gene 3 (LAG-3), with patient’s prognosis." (PMID 33072595, 2020). "Given the immunosuppressive effects of inhibitory immune checkpoints including PD-1, CTLA-4, and LAG3, and their published role in tumor escape this association seems paradoxical." (PMID 32861198, 2020). "Our results are in line with a current meta-analysis, which demonstrated an association of LAG3 expression with better outcome in diverse tumor entities." (PMID 32861198, 2020). "The first group (approximately half of the tumors, generally at more advanced T stages) was characterized by a high fraction of LAG-3+ T lymphocytes as well as other tumor-associated immune cells." (PMID 32582215, 2020). "Early reports based on LAG-3 deficient mice showed that NK cells from these mice were defective in their ability to lyse certain tumor targets, suggesting a role for this receptor in facilitating NK cell killing." (PMID 32153582, 2020). "After infiltrating tumor-specific lymphocytes, co-expression of LAG-3 and PD-1 causes immune exhaustion and growth of the tumor." (PMID 33167514, 2020). "Our preliminary results had shown an association of LAG3 promoter hypomethylation with increased levels of tumor infiltrating immune cells, whereas infiltration of immune cells was correlated with hypermethylation of the downstream CTCF binding site." (PMID 32861198, 2020). "LAG-3 is expressed in association with other immune checkpoint molecules in the tumor microenvironment, therefore chronic viral infection serves as a model for T cell exhaustion in tumor-associated lymphocytes." (PMID 30788290, 2019). "LAG-3 expression is often observed on tumor-infiltrating lymphocytes (TILs) and is associated with shorter progression-free survival in patients treated with anti-PD-1 therapy, suggesting independence of these immune evasion pathways." (PMID 31569553, 2019). "Another cell surface marker, lymphocyte-activation gene 3 (LAG3), was targeted for localisation of tumour infiltrating T-cells in mice models bearing the human variant of the LAG3 (MC38/hLAG3)." (PMID 31656546, 2019). "Pre-clinical studies demonstrated that combination blockade of PD-1 and LAG-3 can induce immune activation and associated tumor rejection in fibrosarcoma and colorectal cancer models in mice." (PMID 30941125, 2019). "NK cells from LAG-3-deficient mice show defects in killing of certain tumor targets, whereas lysis of MHC class I-mismatched cells was not affected by LAG-3 deletion." (PMID 30250471, 2018). "As a result, expression of CD39, A2AR, A2BR, ICOS and LAG-3 was higher on tumor-associated CD8+ T cells from young, compared to elderly, IL-2/CD40-treated mice." (PMID 30560130, 2018).
tumor (continued). "The objective response rate (ORR) was 11.5% in 61 efficacy-evaluable patients, and a correlation of higher ORR with a LAG-3 expression above 1% on tumor-associated immune cells was shown." (PMID 29535740, 2018). "The tested EBL animals developed monoclonal or oligoclonal expansion of B cells in peripheral blood (data not shown); therefore, these observations indicate that PD-1+LAG-3+ T cells can be functionally exhausted and are associated with the tumor development." (PMID 29914540, 2018). "One such target is LAG-3, which is upregulated on T cells that have experienced repeated antigen exposure, such as in the tumor microenvironment (TME), and is associated with reduced T cell effector function." (PMID 30400822, 2018). "In a recent phase I/II clinical study a combination of LAG-3 Ig and peptides from five tumor-associated antigens was able to induce antigen-specific CD4 and CD8+ T cell responses in metastatic melanoma patients." (PMID 29033936, 2017). "We demonstrated that PD-1+ and LAG-3+ TILs were present in approximately 30% and 18% of TNBCs, respectively, and that their presence in the tumor microenvironment tended to be associated with good prognosis in TNBC." (PMID 27912781, 2016). "We have studied three genes associated to T cell exhaustion and all of them (lag3, pd1 and tim3) were downregulated in tumor infiltrating lymphocytes from NLGP-treated mice." (PMID 23326300, 2013). "The expression of LAG-3 on TILs in certain CRC tissues has been linked to advanced tumor stages, microsatellite instability-high (MSI-H), and poor prognosis, suggesting that LAG-3 could serve as a potential prognostic marker for CRC." (PMID 40255905, 2025). "In addition, we identified a correlation of PD-1 and LAG-3 expression between tumor-associated and peripheral immune cells, which was independent of the subtype." (PMID 40148963, 2025). "We speculate that LAG3 may mediate an as-yet-undefined pathway associated with the higher expression of anti-tumor KIRs in CD8 + T cells." (PMID 40411616, 2025). "In this context, germline LAG3 variation may represent a stable genetic factor predisposing to inadequate immune surveillance and tumor persistence." (PMID 41614836, 2025). "(E–I) The relationship between risk scores and CD39, CD8+, CD8+LAG3+, tumor size, and T stage." (PMID 40928500, 2025). "Major barriers include the immunosuppressive tumor microenvironment (TME); heterogeneous or low antigen expression; antigen loss; poor tumor infiltration; and T cell exhaustion driven by the persistent stimulation of inhibitory receptors, such as PD-1 and LAG-3." (PMID 40563595, 2025). "Similarly, tumor-infiltrating T lymphocytes have high levels of several inhibitory co-receptors, including LAG-3, and are continuously exposed to tumor-associated antigens, which results in functional exhaustion." (PMID 41357215, 2025). "Tumours with LAG‐3 expression are usually associated with low survival." (PMID 40415479, 2025). "For instance, Lag3, a gene associated with the suppression of antitumor functions and known to act as a receptor for the ligand LSECtin59, blunting tumor-specific immune responses, was incorrectly inferred to follow a pattern of initial downregulation followed by upregulation in the original study." (PMID 41022768, 2025). "Based on these discoveries, we applied receiver operating characteristic (ROC) curve analysis to evaluate the diagnostic accuracy of LAG3 expression in discriminating KIRC tumor tissue from normal tissue, as well as different clinicopathological characteristics." (PMID 38277212, 2024). "Importantly, they also observed reduced tumor growth and enhanced survival in LAG‐3/PD‐1 double deficient mice in several models." (PMID 39560030, 2024). "Furthermore, increased infiltration of LAG-3+ tumor-infiltrating lymphocytes in metastatic sites is linked to shorter PFS under PD-1 blockade (p = 0.07)." (PMID 39743998, 2024).
tumor (continued). "Additionally, we found that higher LAG3 expression in tumor-infiltrating lymphocytes (TILs) was associated with shorter OS (HR = 1.16, 95% CI 1.02–1.31, P = 0.021)." (PMID 38041068, 2023). "Interestingly, this has also been suggested by earlier work where NK cells isolated from a murine model with LAG-3 deficiency exhibited defects in NK cell mediated anti-tumor immunity." (PMID 38090565, 2023). "Moreover, LAG3 + immune cell density is associated with various parameters, including sex, tumor location, Lauren phenotype, and HER2-, EBV-, MSI, and PD-1/PD-L1 status in PR-GC." (PMID 37311986, 2023). "However, there are limited studies, that showed the association of tumor-infiltrating LAG3 + T cells with CRC prognosis, their results were controversial." (PMID 36765348, 2023). "While the method is yet to be applied to the analysis of exhaustion per se, single-cell RNA-seq analysis has shown that day 7 patient-derived tumour organoids do express exhaustion markers, i.e. PD-1, LAG-3 and TIM-3, underlining the potential value of this approach." (PMID 37554723, 2023). "In UM, a high level of LAG-3 was found to be associated with high-risk tumor parameters." (PMID 37237550, 2023). "Interestingly, in EGFR-mutant adenocarcinomas, expression of TIM-3, PD-1, and LAG-3 is lower and shows limited association with tumor mutational burden." (PMID 37567938, 2023). "Tumor-derived antigens increase LAG-3 expression, leading to CTL deficiency." (PMID 37853449, 2023). "Similarly, a previous study on CRC also demonstrated that LAG3 + T lymphocytes in tumor tissue were associated with higher invasion depth and metastasis." (PMID 36765348, 2023). "We identified several markers specifically expressed in the C0 cluster that was tumor-infiltrated, such as checkpoint inhibitor (LAG3), cytotoxicity-associated genes (GZMK), and oncogenic driver gene (FXYD2), further indicating that these CD8+ T cells were exhausted." (PMID 35812372, 2022). "Triggering of LAG-3 causes suppressed T cell activation and T cell-mediated cytokine secretion, which functionally synergize with the immunosuppressive activity of PD-1 to promote tumor immune escape." (PMID 35328630, 2022). "All these cell types participate in the establishment of the tumor-associated immune (TIL) microenvironment in which overexpression of LAG3 has been observed, so it could be a valuable target of immunological therapy in cancer patients." (PMID 36013315, 2022). "In addition, LAG3 has also been found to be expressed on the surface of B cells, tumor-associated macrophages, and other cells." (PMID 36042469, 2022). "Moreover, the frequency of LAG-3 in tumor tissues was associated with differentiation, lymph node metastasis, and invasion in CRC patients." (PMID 35655158, 2022). "In addition, in this study the expression of HLA family members and several immunotherapy-related target genes, such as CD274 (PD-L1), CTLA-4, and LAG-3, was elevated in the tumor environment of the high-risk group compared with the low-risk group." (PMID 36081499, 2022). "In primary tumors, the LAG3 subtype was associated with a worse prognosis and a more immunosuppressive microenvironment, as defined by higher infiltration with exhausted T cells and tumor associated macrophages." (PMID 36313654, 2022). "Additionally, the expression of multiple inhibitory receptors such as CTLA-4, TIGIT, LAG3, PD-1, and PD-L1 suggests that the tumor-acquired resistance was associated with T cell exhaustion in BCG-induced HLA-I+ tumors." (PMID 35503263, 2022). "LAG-3 has been found to be expressed on tumor-infiltrating T cells in PC, and its expression is associated with poor disease outcomes Consequently, clinical studies are investigating the inhibitory effect of LAG-3 in solid cancers." (PMID 36106025, 2022).
tumor (continued). "Surprisingly, they found that Lag-3 null mutation resulted in decreased NK cell cytolytic activity against Yac-1, IC-21, and J77 tumor cell lines, suggesting that LAG-3 might act as a co-stimulatory receptor on mouse NK cells." (PMID 34503073, 2021). "When comparing specific immune cell subtypes that are tumor-associated, i.e., significantly higher in proportion than in the normal controls, immunosuppressive myeloid cells and LAG3-high effector T cell populations were consistently more prevalent in the liver metastatic microenvironment." (PMID 33985562, 2021). "Additionally, LAG-3 expression on TILs in the tumor center was associated with better differentiation (grade 1, p = 0.021)." (PMID 34442393, 2021). "Interestingly, it has been shown that LAG3 promoter hypomethylation positively associates with increased levels of tumor-infiltrating immune cells and better PFS in CM patients." (PMID 34575678, 2021). "The immune checkpoints (i.e., PD1, CTLA4, and LAG3) were upregulated in the high-risk group, which might induce the depletion of CTLs, the tumor immune escape, and poor survival outcome." (PMID 33791227, 2021). "Inhibition of GSK-3β leads to the loss of LAG-3 on T cells and enhanced tumor clearance." (PMID 34356465, 2021). "Furthermore, the expression of LAG-3 in tumor-infiltrating γδ T cells was associated with earlier relapse and shorter overall survival." (PMID 34572874, 2021). "While, CMS1 tumors exhibit potent anti-tumor activity, transcription of genes encoding ICs such as PDCD1, CD274, CTLA4, and LAG3 may aid tumor immune escape in these tumors." (PMID 33477864, 2021). "In the need of novel strategies, in vivo studies provided convincing evidence that a dual blockade against PD-1 and the novel immune checkpoint receptor lymphocyte-associated gene-3 (LAG-3) can result in tumor reduction and increase of survival by restoring CD8+ T cell function." (PMID 33413541, 2021). "Therefore, an increased level of LAG-3 expression is often associated with T cell exhaustion, leading to lower T cell activity and decreasing their ability to activate or secrete anti-tumor cytokines." (PMID 33925941, 2021). "Based on in vivo experiments, loss of the FGL1/LAG3 interaction could be achieved by gene knockout or antibody blockade, and antitumor immunity could be promoted by stimulating tumor-infiltrating lymphocyte (TIL) activation and expansion in the TME." (PMID 34526102, 2021). "Additionally, elevated LAG3 expression was linked to a significantly better outcome for patients in the advanced tumour stages subgroup." (PMID 32592066, 2020). "Considering the phenomenon of LoY apparently correlating with LAG3 as a marker of the tumor microenvironment in EAC could also implicate a direct influence of Y deficient leukocytes on the tumor immune microenvironment in cancer." (PMID 32629877, 2020). "The contradictory observations made about the prognostic value of LAG-3 expression in cancer patients could be associated to the difference in evaluated tumor type." (PMID 33374804, 2020). "In addition, it remains obscure why only advanced tumour stages revealed a prognostic impact of LAG3 in contrast to early stages, underlining the urgent need for further research on immunomodulation." (PMID 32592066, 2020). "In the present study, LAG3-positive T cells, which are associated with a better prognosis after anti-PD-1 therapy, might have included an exhausted subset that is tumour-specific and can be reinvigorated by PD-1/PD-L1 blockade." (PMID 32203221, 2020). "Furthermore, compared with tumor NK cells, tumor ILC1s express higher levels of the genes encoding PD-1 and LAG-3, which repress bioenergetics and mitochondrial biogenesis in T cells." (PMID 32983138, 2020). "Moreover, tumor growth was more likely to be reduced in both LAG-3- and PD-1-deficient mice, that when the single knockout of one of these molecules was performed." (PMID 31717326, 2019).